CRP (C-reactive protein)
Diseases named in the same sentence as CRP in open-access papers (continued):
Sharing a sentence is not in itself a finding about the gene and the disease.
neuropathy (38 papers, 2010 to 2025). A disorder affecting the nervous system that manifests with pain, tingling, numbness, and/or muscle weakness. "An association between neuropathy and CRP has been reported by us and others." (PMID 21941527, 2011). "Compared with the CRP-high group, neuropathy and dysgeusia occurred significantly more frequently in the CRP-low group." (PMID 38730675, 2024). "TNF-α is a pro-inflammatory cytokine whose involvement in neuropathy is more obvious than those of IL-6 or C-reactive protein." (PMID 37629665, 2023). "ABI was linked to neuropathy and 6-MWD, exacerbations depended on FEV1, 6-MWD and CRP." (PMID 31959163, 2020). "Also G4 revealed a higher prevalence of neuropathy (P = 0.008) with increased inflammatory marker CRP in both G3 and G4 compared to G1 and G2 (P = 0.0001)." (PMID 28546831, 2017). "Moreover, compared with diabetic patients who have painless neuropathy those with PDN have been shown to have higher levels of C-reactive protein, considered to be a biomarker for any inflammatory process." (PMID 24961298, 2014). "Although there is limited data on elevated CRP levels in diabetic patients with neuropathy or retinopathy, thus linking inflammation with the emergence of microvascular complications, the CRP ratio could serve as a biochemical indicator for the advancement of retinopathy or neuropathy." (PMID 40475072, 2025). "Furthermore, according to data from a large cohort study where participants were monitored for one year, hs-CRP levels above 2.5 mg/L could predict neuropathy complications in T2DM." (PMID 35620114, 2022). "Therefore, the evaluation of hematological parameters and the concentration of serum CRP could be useful in the diagnosis of neuropathy." (PMID 31341489, 2019). "Severity of neuropathy (NSS, NDS scores, visual analogue scale), cutaneous microcirculation (MC) parameters and inflammatory markers (ILs, CRP, TNFα) were assessed before and after treatment." (PMID 32825324, 2020). "Additional studies, including erythrocyte sedimentation rate (ESR), C-reactive protein (CRP), thyroid-stimulating hormone (TSH), vitamin B12, and folic acid, were performed to rule out other causes of neuropathy, all of which were within normal limits." (PMID 41018342, 2025). "In this study, though the total number of AE profiles was acceptable, the incidence of non-hematological AEs, including neuropathy and dysgeusia, was found to be significantly higher in the CRP-low compared to the CRP-high group." (PMID 38730675, 2024). "Subsequently, a recent study confirmed the previous works by reporting increased C-reactive protein levels in diabetic neuropathy subjects compared to those of the diabetic patients without neuropathy." (PMID 37762893, 2023). "In addition, epidemiological studies have reported a positive correlation between serum levels of TNF-α, C reactive protein (CRP), and erythrocyte sedimentation rate (ESR) in patients with neuropathy." (PMID 31341489, 2019).
diabetic retinopathy (37 papers, 2009 to 2026). "The gene variant rs2808629 for CRP was shown to be associated with the susceptibility to develop diabetic retinopathy in T2D patients for over 10 years." (PMID 41010041, 2025). "This study demonstrated that the CRP/albumin ratio is a significant inflammatory marker in diabetic retinopathy and is associated with disease progression." (PMID 40941666, 2025). "Our study elucidated the association between the risk of diabetic retinopathy (DR) and the CRP/HDL-C ratio in patients with T2DM, the higher CRP/HDL-C levels were correlated with the higher risk of DR." (PMID 40104822, 2025). "The results of these studies agreed with a meta-analysis, in which higher CRP levels were associated with the presence and severity of diabetic retinopathy." (PMID 30281641, 2018). "The association between higher serum concentrations of CRP and higher frequency and level of diabetic retinopathy has also been addressed in previous investigations, which also included other than East-Asian populations." (PMID 30281641, 2018). "Hitherto, the present study is largest one, and the one with a population-based recruitment of participants, which assessed associations between the serum concentration of CRP and diabetic retinopathy." (PMID 30281641, 2018). "Therefore, the measured CRP levels are presumed to be largely associated with diabetic retinopathy and its related inflammation." (PMID 40941666, 2025). "Elevated levels of serum C-reactive protein have been linked with serious diabetic retinopathy." (PMID 37762893, 2023). "Furthermore, clinical studies showed elevated serum concentrations of fetuin-A, vascular endothelial growth factor, and CRP in T2DM patients with diabetic retinopathy (DR), suggestive of the increased risk of DR with high CRP level." (PMID 29951057, 2018). "Furthermore, in another large population-based cohort, named the Hoorn Study, the authors analyzed 625 patients and verified that the higher circulating levels of CRP were associated with the risk and the development of diabetic retinopathy and its complications." (PMID 33213461, 2020). "First, to our knowledge, this study is the first to report the relationship between the CRP/HDL-C ratio and the risk of diabetic retinopathy in T2DM patients, which provides a new sight for predicting the incidence of retinopathy." (PMID 40104822, 2025). "Although the relationship between C-reactive protein (CRP) and diabetic retinopathy (DR) has been investigated in several studies, the results remain inconsistent and certain aspects are still unclear." (PMID 40941666, 2025). "The level of C-reactive protein (CRP) can be employed to evaluate the extent of diabetic retinopathy (DR)." (PMID 38143687, 2023). "These associations remained significant after full multivariable adjustment, including for diabetic retinopathy and CRP." (PMID 34160658, 2021). "The choroidal thickness in the CRP (+) group was thinner than that in the CRP (−) group except for the outer nasal sector of the Early Treatment Diabetic Retinopathy Study (ETDRS) grid." (PMID 33564690, 2021). "CRP is a clinically recognized marker of inflammation, however, other proteins are also proposed as useful markers of diabetic retinopathy." (PMID 33504108, 2021). "For instance, the Justification for the Use of Statins in Primary Prevention: an Intervention Trial Evaluating Rosuvastatin (JUPITER) trial found that higher serum levels of CRP and IL-1β were correlated with diabetic retinopathy." (PMID 33213461, 2020). "The finding of increased CRP concentrations with DR is also in agreement with the notion of diabetic retinopathy as an inflammatory disease." (PMID 30281641, 2018). "We did indeed observesignificantly higher Hs-CRP levels among patientswith diabetic retinopathy compared with others." (PMID 26136138, 2015).
diabetic retinopathy (continued). "Recently, the role of growth factors, CRP, proinflammatory cytokines, or level of lipids has been emphasised in the pathogenesis of diabetic retinopathy in children." (PMID 24381412, 2013). "CRP is produced by the liver, biologically activating the complement system, and is known to be upregulated in systemic inflammation, cardiovascular diseases, and diabetes as well as diabetic retinopathy." (PMID 41010041, 2025). "There may be a positive correlation between hs-CRP concentration and the prevalence of diabetic retinopathy (r = 0.617, P < 0.01)." (PMID 38027115, 2023). "The association was attenuated in the fully adjusted model including diabetic retinopathy and CRP." (PMID 34160658, 2021). "Similar relationship could be observed in another independent research, which showed that CRP embraced a positive relationship with diabetic retinopathy." (PMID 33213461, 2020). "This may be important since the CRP concentration as well as the presence and severity of diabetic retinopathy depend on a multitude of parameters." (PMID 30281641, 2018). "As a consequence, our findings suggest that GDF-15 might be linked to diabetic retinopathy through mechanisms independent of CRP." (PMID 33239667, 2020). "However, the relationship between MBL levelsand diabetic retinopathy persisted on additional adjustment for Hs-CRP, which indicates thatCRP and MBL may carry different types of information asmarkers of inflammation." (PMID 26136138, 2015). "Previous studies have demonstrated the elevated blood levels of CRP in patients with T1DM and T2DM suffering from diabetic complications, such as diabetic retinopathy (DR)." (PMID 33504108, 2021). "Some traditional pro-inflammatory factors, such as C-reactive protein (CRP) and IL-1β, is being identified as the novel therapeutic targets of diabetic retinopathy." (PMID 33213461, 2020). "To date, the relationship between C-reactive protein (CRP) level and diabetic retinopathy (DR) remains controversial." (PMID 26636823, 2015). "These limited samples showed the differences between normal and diabetic samples, including those relevant to diabetic retinopathy such as vascular endothelial growth factor (VEGF), C reactive protein, glutathione, and cytokines." (PMID 19145248, 2009). "On the other hand, the median height, blood Hb and Htc, serum albumin, C-reactive protein, HbA1c, and fasting glucose of the patients with and without diabetic retinopathy were significantly different (p < 0.05 for all)." (PMID 37762893, 2023). "Some processes relevant to diabetic retinopathy were found upregulated in diabetic aqueous samples including CD40, C reactive protein, erythropoietin, fatty acid binding protein, FGF basic, fibrinogen, IL-1ra, IL-8, leptin, macrophage-derived chemokine (MDC), MMP-2, and VEGF." (PMID 19145248, 2009). "In patients with T1DM and retinopathy, a five-fold higher level of CRP protein was detected in the blood serum compared to the group of patients with T1DM and without diabetic retinopathy." (PMID 33504108, 2021).
Glucose intolerance (37 papers, 2008 to 2026). Glucose intolerance (GI) can be defined as dysglycemia that comprises both prediabetes and diabetes. "Due to the lack of postpartum glucose data in our study, we were unable to assess the association between postpartum glucose intolerance and milk CRP." (PMID 35277026, 2022). "Since 2-hour glucose is an indicator of glucose tolerance, this study indicated CRP gene is associated with glucose intolerance." (PMID 28801571, 2017). "Since 2-hour glucose is an indicator of glucose tolerance, our finding suggests an association of CRP gene with glucose intolerance." (PMID 28801571, 2017). "There seems to be a significant implication of inflammatory markers such as CRP and SAA in the causal relationship between sleep loss and glucose intolerance." (PMID 35494895, 2022). "Descriptive analysis identified three baseline characteristics - age ≤ 60 years, presence of glucose intolerance and CRP levels ≤ 0.04 mg/dL - which differed between progressors and non-progressors." (PMID 20673337, 2010). "In summary, our findings suggest that individuals with lower CRP levels and with glucose intolerance at baseline were the ones who will benefit from this relatively simple intervention in terms of glucose metabolism, independent of body adiposity." (PMID 20673337, 2010). "A prior systematic review documented that inflammatory markers such as C-reactive protein (CRP) and serum amyloid A (SAA) might be the significant mediators in the causal relationship between sleep loss and glucose intolerance." (PMID 36793924, 2023). "Many lifestyles risk factors as well as non-modifiable risk factors contribute to the association between GDM and related CVD, including high blood sugar, glucose intolerance, unfavorable lipid profiles, advanced age, and higher levels of C-reactive protein (CRP)." (PMID 37760871, 2023). "Also they found that the main factors which affect hs-CRP levels were glucose intolerance and weight gain during pregnancy." (PMID 27385967, 2016). "Regression analyses were used to determine the relationship between VO2max and BMI-corrected HS with glucose intolerance, HOMA-IR, MATSUDA, MetS (both MetS-BMI and MetS-WC) and CRP at 1-year postpartum." (PMID 41276872, 2025). "This meta-analysis demonstrated that administration of L-carnitine in diabetic and glucose intolerance patients can significantly reduce TG, LDL-C, FBG, HbA1c, HOMA-IR, CRP, TNF-α, weight, BMI, BFP, and leptin levels." (PMID 39085907, 2024). "Accordingly, we noted that doxepin treatment led to increases in serum CRP, IL-1β, and TNF-α levels in our doxepin-treated mice, in parallel with glucose intolerance exacerbation." (PMID 33809508, 2021). "Baseline characteristics of the non-progressors and progressors were similar, except for the higher percentage of individuals in the age group < 60 years, with glucose intolerance (IFG or IGT) category and in the lower tertiles of CRP levels." (PMID 20673337, 2010). "Lower CRP levels and diagnosis of glucose intolerance at baseline were predictors of non-deterioration of the glucose metabolism after a relatively simple intervention, independent of body adiposity." (PMID 20673337, 2010). "In the final logistic regression model, the diagnosis of glucose intolerance (IFG or IGT) and CRP levels < 0.04 mg/dL at baseline were predictive of non-deterioration of glucose tolerance following the intervention program, adjusted for age ≥ 60 years." (PMID 20673337, 2010).
left ventricular hypertrophy (37 papers, 2006 to 2026). Enlargement of the LEFT VENTRICLE of the heart. "Numerous adult studies have shown correlations between hs-CRP and left ventricular mass or risk for left ventricular hypertrophy." (PMID 40507658, 2025). "Beyond CRP, increased expression of various inflammatory cytokines has been associated with adverse cardiac remodelling including left ventricular hypertrophy, fibrosis, and development of heart failure." (PMID 38997620, 2024). "In a large cohort study of PD patients, inflammation determined by level of C-reactive protein and left ventricular hypertrophy synergistically increased the risk of all-cause mortality and cardiovascular death." (PMID 37779359, 2023). "The elevated level of CRP is also associated with left ventricular hypertrophy and left atrial enlargement." (PMID 35535358, 2022). "A positive association of left ventricular hypertrophy with high-sensitive CRP in hemodialysis patients has been reported." (PMID 25591903, 2015). "Under oxidative stress conditions, the decline of antioxidant enzyme activities exaggerated CRP, hs-cTnI, and hs-cTnT levels, indicating left atrial enlargement followed by left ventricular hypertrophy." (PMID 35535358, 2022). "We have previously published the association between left atrial enlargement and left ventricular hypertrophy with ANP and BNP, but herein, the CRP observation is extended to left atrial enlargement and left ventricular hypertrophy due to the aortic and mitral valve dysfunction." (PMID 35535358, 2022). "suPAR was associated with low LVEF and elevated BNP, but not with left ventricular hypertrophy, independent of CRP, renal function, and diuretic use among cardiac inpatients who were not undergoing chronic hemodialysis." (PMID 28135310, 2017). "In the univariate Cox regression analysis all-cause mortality, showed a positive relationship with age, left ventricular hypertrophy (LVH), prevalent cardiovascular disease, new CV events, the Charlson comorbidity index, smoking, and the highest tertile of serum OPG, troponin-I, BNP and CRP." (PMID 28882110, 2017). "Higher levels of highly-sensitive C-reactive protein (hs-CRP) and circulating endothelial cells in CAH patients, as well as left ventricular hypertrophy and prolonged mitral deceleration time." (PMID 35399922, 2022). "Furthermore, due to its retrospective nature, the impact of the related clinical factors on PCAT CT attenuation, such as serum highly sensitive C-reactive protein level, left ventricular ejection fractions, left ventricular hypertrophy, etc., could not be investigated in our study." (PMID 35310984, 2022).
bladder cancer (36 papers, 2005 to 2025). "YKL-40 was associated with the risks of liver and bladder cancers, clearly outperforming CRP for these cancers." (PMID 40188292, 2025). "The modified Glasgow Prognostic Score based on C-reactive protein and albumin has been proved to be associated with the risk of recurrence of bladder cancer." (PMID 39039528, 2024). "In looking towards the future of CRP as a tool for risk stratification of bladder cancer, it is important to understand CRPs role when included in other scoring systems." (PMID 34512646, 2021). "For bladder cancer, CRP levels are associated with disease progression in NMIBC and with stage and survival for MIBC." (PMID 34512646, 2021). "In a prospective study of 67 patients with inoperable bladder cancer, CRP was measured one day prior to initiation of chemotherapy (gemcitabine and cisplatin); elevated CRP was associated with both shorter PFS and shorter OS." (PMID 34512646, 2021). "In patients with advanced bladder cancer undergoing chemotherapy elevated CRP levels were shown to be associated with a poor clinical outcome." (PMID 23497335, 2013). "Moreover, in patients with advanced bladder cancer undergoing chemotherapy elevated CRP levels were shown to be associated with a poor clinical outcome." (PMID 22958305, 2012). "CRP and urea concentrations were elevated in high-grade (4.85 and 40.66, respectively) bladder cancer patients compared to the control group (1.25 and 29.96; p = 0.001 and p = 0.028, respectively)." (PMID 39766111, 2024). "Long-term accumulation of toxins and glycation end products in patients with bladder cancer will increase the body's inflammatory factors, such as IL-6, CRP, TNF-α, and other acute reactive proteins." (PMID 35075365, 2022). "This study aimed to assess the prognostic value of the lymphocyte–C-reactive protein ratio (LCR) in patients with bladder cancer (BCa) who underwent radical cystectomy (RC)." (PMID 34778081, 2021). "For bladder cancer, the data suggest CRP is a useful biomarker, which can provide additional prognostic information when combined with existing metrics." (PMID 34512646, 2021). "The value of CRP as a prognostic indicator for patients with bladder cancer has been assessed in multiple clinical states." (PMID 34512646, 2021). "A previous study evaluating the effect of the CRP/albumin ratio on overall survival after radical cystectomy in bladder cancer patients found that a high CRP/albumin ratio was the most effective prognostic indicator." (PMID 33193910, 2020). "We further tested the relationship of GPS with CRP and concomitant bladder cancer for the prognostic impact in patient with UTUC." (PMID 29348903, 2017). "Meanwhile, it is the first meta-analysis to evaluate the prognostic role of CRP in urothelial carcinoma/bladder cancer." (PMID 26235332, 2015). "Nevertheless, the results of the present study are consistent with previous pre-/postoperative C-reactive protein findings in colorectal, pancreatic and bladder cancer." (PMID 17003778, 2006). "In the present study, both tumour grade and the presence of a systemic inflammatory response, as evidenced by elevated circulating concentrations of C-reactive protein, were independent predictors of cancer-specific survival in patients with bladder cancer." (PMID 15726119, 2005). "YKL-40 exhibited superior prognostic ability compared to CRP for liver and bladder cancers." (PMID 40188292, 2025). "Recent studies showing that elevated C-reactive protein or pyuria, a result of an increased inflammatory response, are useful in predicting poor prognosis of bladder cancer and may also be related to these hypotheses." (PMID 34575374, 2021). "Similarly, a study of 80 patients with advanced, inoperable bladder cancer undergoing second line MVAC chemotherapy concurred that patients whose CRP normalized after chemotherapy also had improved overall survival as compared to the non-normalized group." (PMID 34512646, 2021).